SMIM32 (small integral membrane protein 32)
Gene: Protein-coding gene on chromosome 5 (136,191,468 to 136,193,162, reverse strand). Ensembl gene ENSG00000271824.
Subcellular location: Membrane
Gene Ontology:
Cellular component: membrane
Homologues: Orthologues: chimpanzee SMIM32 (100% identical), macaque SMIM32 (99% identical), rabbit SMIM32 (95% identical), mouse Smim32 (93% identical), pig SMIM32 (93% identical), rat Smim32 (92% identical), guinea pig SMIM32 (91% identical), dog SMIM32 (89% identical).
Diseases named in the same sentence as SMIM32 in open-access papers:
SMIM32 is named in the same sentence as 2 diseases in open-access papers, as found by Europe PMC text mining. Sharing a sentence is not in itself a finding about the gene and the disease. The quoted sentences say what the papers report.
pancreatic cancer (1 paper, 2021). "There has been no study concerning the modulation of SMIM32 in pancreatic cancer, which is a potential protective biomarker and is worth exploring in the future." (PMID 34290570, 2021).
SMIM32 also shares sentences with these, for which no sentence is quoted: tumor (1 paper).